INS (insulin)
Diseases named in the same sentence as INS in open-access papers (continued):
Sharing a sentence is not in itself a finding about the gene and the disease.
diabetes (continued). "But insulin, hypertension, BMI, age, and duration of diabetes were significant difference between DR and normal." (PMID 30367589, 2018). "The app combines several features, many of which are found in other diabetes devices, such as insulin pumps and glucose meters, or offered as stand-alone functions in mobile apps." (PMID 30470680, 2018). "The evaluation of several patient-centered dimensions, such as hypoglycemia awareness and fear, is expected to support clinicians on tailoring insulin treatment and improving patient education and diabetes management." (PMID 30479669, 2018). "To further pinpoint the molecular mechanism of the observed diabetes, we assayed insulin (Ins1 and Ins2) expression levels in total pancreas derived from WT and Cosmc-KO animals." (PMID 30305605, 2018). "Insulin secretion from pancreatic β cells is critical for the proper maintenance of blood glucose levels, and perturbations in this process lead to diabetes." (PMID 29577067, 2018). "The current life-saving therapy consists of exogenous insulin administration, but it is, however, unable to prevent diabetes’ long-term side effects, including nephropathy, peripheral neuropathy, and vascular alterations." (PMID 30223606, 2018). "Consistent with this view, recent work in our laboratory has shown that therapeutic natural and stable analogues of apelin-13 stimulate insulin secretion, enhance cellular glucose uptake and improve acute glucose tolerance in animal models of obesity-diabetes." (PMID 30157220, 2018). "In HCHS/SOL, an additional N = 344 individuals reported a diabetes diagnosed between 22 and 45 years of age, only 30% of which were taking insulin by the baseline examination." (PMID 30305909, 2018). "It seems plausible that the same mechanisms of action would operate in patients with established diabetes and lead to a delay in the need for starting insulin treatment." (PMID 30327785, 2018). "Oral cinnamon extract reduced fasting glucose, triglycerides, low-density lipoprotein (LDL), and total cholesterol in patients with type 2 diabetes mellitus, as well as improved insulin sensitivity in women with PCOS." (PMID 30340496, 2018). "As we know, diabetes can be broadly subdivided by etiology into T1DM resulting from insulin deficiency and T2DM from resistance to insulin action." (PMID 29736193, 2018). "Diabetes mellitus is a disorder accompanied by an increased glucose level and hyperlipidemia along with problems in insulin and erythrocytic hemoglobin glycosylation." (PMID 30510626, 2018). "General users’ tendency to use the blood glucose and insulin functions longer showed the need for a reliable app service for diabetes management." (PMID 29631989, 2018). "The brain is an important target for insulin, and there is great interest in understanding how diabetes affects the brain." (PMID 30054579, 2018). "Insulin’s introduction to the UK was a catalyst for the formation of large out-patient clinics for diabetes follow-up, with such institutional forms providing new specialist functions for general hospitals." (PMID 29514263, 2018). "Diabetes mellitus (DM) is a disease characterized by chronic hyperglycaemia and disturbances of carbohydrate, fat and protein metabolism resulting from an absolute or relative deficiency of insulin." (PMID 30287729, 2018). "Diabetes is a lifelong course disease, so insulin treatment has to be effective and safe, and patients should be satisfied with it." (PMID 29755520, 2018). "Clinically, DM is a progressive multisystemic disorder characterized by myotonia, muscle weakness, cataracts, and cardiac arrhythmia that can evolve to cardiomyopathy, insulin insensitivity and diabetes, testicular failure, and hypogammaglobulinemia." (PMID 30425655, 2018).
diabetes (continued). "Although insulin regimen, continuous insulin infusion, and strict blood glucose monitoring have made great progress in the treatment of diabetes mellitus, it remains difficult to achieve physiologically precise regulation of blood glucose." (PMID 30345316, 2018). "He had been treated for hypothyroidism secondary to Hashimoto’s disease and type 2 diabetes mellitus with insulin self-injection therapy before undergoing treatment of malignant melanoma." (PMID 29914537, 2018). "At baseline, 88% of CCI participants were prescribed diabetes medication (57% were prescribed a diabetes medication other than metformin, 30% prescribed insulin) and 93% were obese." (PMID 29417495, 2018). "Our data indicate, that CHI patients with diabetes often require an intensive insulin therapy comparable to that of type 1 diabetic patients, particularly when diabetes progresses and residual beta cell function further declines." (PMID 30577875, 2018). "We have demonstrated for the first time a reduction in insulin signaling pathway proteins PI3-K/Akt/mTOR pathway in the brain of STZ treated rats that may be implicated as a dominant factor in neurodegeneration leading to cognitive dysfunction seen in diabetics." (PMID 30041644, 2018). "The HAT study in Brazil evaluated the frequency and incidence rate of hypoglycemia in a cohort of patients with insulin-treated diabetes mellitus." (PMID 30479669, 2018). "The removal of Dicer1 in β-cells also lead to reduced insulin content, reduced insulin secretion and development of diabetes during aging." (PMID 30551650, 2018). "Insulin is indicated in known patients with T2DM if the HbA1c level remains persistently above 10.0% (86 mmol/mol) or uncontrolled diabetes with respect to predefined goals in spite of optimizing the oral antidiabetic drugs (OADs)." (PMID 29508275, 2018). "Patients with type 2 diabetes mellitus (T2DM) treated with long-acting sulfonylureas (SUs), insulin, or a combination of both are also susceptible to nocturnal hypoglycemia." (PMID 29508275, 2018). "This has revealed the poor quality of diabetes care, especially in insulin-dependent patients, and has helped to build a database of diabetics in the area." (PMID 29670916, 2018). "Our studies in human subjects indicated that INHBE mRNA expression was upregulated under insulin-resistant and obese conditions in subjects with pre-diabetes." (PMID 29596463, 2018). "S100B secretion from adipocytes is related to lipolysis, inhibited by insulin, and thus is subject to dysregulation by diabetes and other metabolic diseases." (PMID 29681765, 2018). "Raccah D. Basal insulin treatment intensification in patients with type 2 diabetes mellitus: a comprehensive systematic review of current options." (PMID 29527102, 2018). "Among the factors above, a long duration of diabetes, high HbA1c levels, and insulin treatment are predictive factors for the deterioration of DR." (PMID 29682578, 2018). "In 2014–2015, the largest international survey of insulin injection technique in patients with diabetes taking insulin was conducted in 42 countries, totaling 13,289 participants." (PMID 30498521, 2018). "Self-measurement and documentation of blood-glucose are critical elements of diabetes management, particularly in regimes including insulin." (PMID 29799861, 2018). "No statistical correlations were found between age, duration of diabetes, daily insulin dose, or BMI of type 1 diabetic patients and various parameters of their GV." (PMID 29725320, 2018). "In the early stage of diabetes mellitus type 2, postprandial hyperglycemia occurs due to impaired secretion of insulin after meal." (PMID 29295712, 2018). "The treatment of Type 2 Diabetes Mellitus (T2DM) consists primarily of oral antidiabetic drugs (OADs) that stimulate insulin secretion, such as sulfonylureas (SUs) and reduce hepatic glucose production (e.g., biguanides), among others." (PMID 29681852, 2018).
diabetes (continued). "In order to fulfill those prerequisites and due to the lifelong course of diabetes, the insulin therapy must be chosen individually in relation to patient's needs, treatment goals, and safety." (PMID 29755520, 2018). "Landmark clinical trials of insulin-treated patients have included SMBG as part of the multifactorial interventions to demonstrate the benefit of intensive glycemic control on diabetes complications." (PMID 29527102, 2018). "Patients with severe IR states typically have either profound compensatory hyperinsulinemia or diabetes which require high levels (over 200 units per day) of exogenous insulin for glycaemic control." (PMID 30131000, 2018). "According to the evolution of the clinical diabetes, after 20 years of having this disease, almost all T1DM patients, 80% of insulin-dependent diabetes patients, and 50% of insulin-independent T2DM patients will have vision loss due to diabetic retinopathy." (PMID 28424632, 2017). "The oral antidiabetic drug metformin (dimethylbiguanide) improves insulin sensitivity primarily via its metabolic actions and is the cornerstone of pharmaco-therapy in type 2 diabetes mellitus." (PMID 28399917, 2017). "Glucagon-like peptide-1 (GLP-1) is a potent gluco-incretin hormone, which plays a central role on pancreatic beta cell proliferation, survival and insulin secreting activity and whose analogs are used for treating hyperglycemia in type 2 diabetes mellitus." (PMID 28767692, 2017). "Diabetes prevention was observed despite lower fasting serum insulin, suggesting the botanical test formula specifically preserved insulin sensitivity." (PMID 28679380, 2017). "The c-peptide is a good index for insulin secretion and clinically related to metabolic syndrome and diabetes." (PMID 29937877, 2017). "Previous reports demonstrated that T has a direct impact on insulin content in the rat, and T administration can protect pancreatic β cells from chemical- induced diabetes." (PMID 28594910, 2017). "Conventional insulin treatment is basically a replacement therapy for the management of diabetes, wherein insulin is exogenously administered by the subcutaneous route to secrete it as in non-diabetic pancreatic secretion." (PMID 28864917, 2017). "Diabetes mellitus (DM) is a chronic endocrine disease resulted from insulin secretory defect or insulin resistance and it is a leading cause of death around the world." (PMID 28531120, 2017). "A high number of patients from both groups receiving insulin detemir and insulin glargine were known diabetics and had high admission blood glucose and HgA1c levels." (PMID 28970434, 2017). "Vanadium is a trace element mainly connected with regulation of insulin metabolism which is particularly important in diabetes." (PMID 28529953, 2017). "Diabetic women taking insulin had lower BMI (24.0 kg/m2) than women regulating diabetes by diet (31.0 kg/m2) or taking oral antidiabetic agents (30.6 kg/m2)." (PMID 27832382, 2017). "In the United Kingdom prospective diabetes study (UKPDS) 34, a significant risk reduction was observed for metformin in diabetes-related end points, all deaths, and stroke, as compared with insulin." (PMID 29017497, 2017). "Fasting glucose ≥ 7.0 mmol/L (126 mg/dL) and/or use of drugs (oral hypoglycemic and/or insulin) defined the diagnosis of diabetes mellitus." (PMID 28355348, 2017). "Mechanism of Cd-induced diabetes remains uncertain but possibly involves damage to insulin-producing β-cells in islets of Langerhans; in pancreas of Cd-exposed rats, such cells secrete substantially less insulin than unexposed ones." (PMID 29348892, 2017). "The median number of years with T2D was 7 (average = 9, SD = 7) and around one fifth of participants were insulin dependent and experienced diabetes specific complications." (PMID 29241444, 2017).
diabetes (continued). "In contrast, because smaller adipocytes secrete more adiponectin and improve sensitivity to insulin, decreasing the size of hypertrophic adipocytes, followed by increasing the number of smaller adipocytes, is considered to be one strategy to treat diabetes." (PMID 28441735, 2017). "Dietary intervention, increased physical activity and exercise, adjustment of insulin therapy, adding other diabetes medications that positively impact body weight, or adding anti-obesity medications are suggested." (PMID 28836234, 2017). "World’s major pharmaceutical industries are in a race to fight against the chronic complications of diabetes and are coming up with different forms of insulin and insulin mimetics." (PMID 28854906, 2017). "It is obvious from this result that the FDF35 group developed diabetes because they were already insulin resistant coupled with hyperinsulinemia, a condition needed to sustain normal blood glucose level." (PMID 28129400, 2017). "Education and counseling on proper insulin pen injection technique should be provided to patients with diabetes using insulin in Nepal." (PMID 29333459, 2017). "Evidence has demonstrated that monomers and formulae improve diabetes and insulin function via multiple targets." (PMID 29164155, 2017). "The patient was diagnosed to have insulin resistance (fasting insulin 186 μIU/mL and fasting C-peptide 14.18 ng/mL) and diabetes mellitus [fasting blood glucose (FBG) 21.0 mmol/L] at the early age of 2 months." (PMID 27612026, 2017). "Poor access to affordable insulin results in serious and needless complications and premature deaths for those with diabetes who need this essential medicine." (PMID 28836974, 2017). "Diabetes mellitus, also known as diabetes, is a chronic disease that is triggered when the body loses its ability to produce enough insulin or use it effectively." (PMID 28957355, 2017). "Though, HbA1c, insulin and β-HCG are useful metabolites for diagnoses and monitoring of diabetes mellitus, yet had fair diagnostic tests values for GDM, since the AUC (95% CI) were >0.05." (PMID 28732072, 2017). "The insulin used for the treatment of diabetics was purified by crystallization, a process first established in 1926." (PMID 28875019, 2017). "The use of PDA should be integrated as part of the training on longitudinality of care whereby HCPs and patients should be made aware that insulin is an option as diabetes progresses and that PDAs are available to help them make this decision." (PMID 28327157, 2017). "Glycaemic traits such as fasting and post-challenge glucose and insulin measures, as well as glycated haemoglobin (HbA1c), are used to diagnose and monitor diabetes." (PMID 28977447, 2017). "ROS impairs insulin-signaling pathways and induces cytotoxicity in pancreatic beta cells, which promotes development of diabetes." (PMID 28430803, 2017). "The conducted studies did not indicate the relationship between the concentration of leptin and adiponectin in the examined sick individuals, both those with newly-diagnosed diabetes and those after implementation of insulin therapy." (PMID 28758947, 2017). "As per the American Diabetes Association guidelines for the management of HHS, she was treated with intravenous fluids and an insulin drip until normalization of blood glucose was achieved and then transitioned to subcutaneous insulin." (PMID 28634594, 2017). "It is a pancreas-specific oxidoreductase which was reported to promote insulin biosynthesis and deregulation of which was involved in the pathogenesis of diabetes mellitus." (PMID 28177904, 2017). "The main factors responsible for the development of type 2 diabetes mellitus (DM II) are the high production of hepatic glucose, impaired insulin secretion, and insulin resistance, which is common in obesity." (PMID 29065507, 2017).
diabetes (continued). "Among inflammatory markers, we found EN-RAGE to be a novel inflammatory marker for pre-diabetes, IL17 for incident T2D and IL13 for pre-diabetes, incident T2D and insulin therapy start." (PMID 29064009, 2017). "Secondly, the sulfonylureas have been regarded as the primary drug for treatment of diabetes mellitus for decades, and the dominating function of sulfonylureas is stimulate insulin secretion by β-cells of pancreatic island." (PMID 28386567, 2017). "Diabetes is a metabolic disorder that indicates elevated blood glucose concentration and occurred by an insufficient of insulin secretion and action." (PMID 29166935, 2017). "Some metabolic disorders such as B-cell dysfunction, impaired insulin secretion, and insulin action contribute to the pathogenesis of diabetes." (PMID 28885566, 2017). "Diabetes mellitus is a metabolic disease characterized by chronic hyperglycemia resulting from defects in insulin secretion, insulin action, or both." (PMID 28930271, 2017). "The reimbursement database of all female patients with type 2 diabetes mellitus under oral antidiabetic agents or insulin from 1996 to 2009 was retrieved from the National Health Insurance." (PMID 27936468, 2017). "Pancreatic β-cell dysfunction, leading to an impaired insulin secretory response to glucose, plays a pivotal role in the transition from prediabetic state to the clinical type 2 diabetes mellitus (T2DM)." (PMID 28386307, 2017). "Subjects with diabetes were comparable for glycated hemoglobin and insulin requirement, defined as total daily insulin dose/weight." (PMID 28880900, 2017). "Third, it has high external validity, including 31 antenatal clinics with variable diabetes technology experience and providing results that are applicable to pregnant women using insulin pumps or multiple daily injections." (PMID 28923465, 2017). "Patient B had hypertension, dyslipidemia, NAFLD, and secondary diabetes requiring >180 units of insulin daily." (PMID 28973478, 2017). "Insulin replacement therapy remains the mainstay of treatment for T1DM, and initial intensive diabetes therapy was associated with a modestly lower all-cause mortality rate when compared with conventional therapy." (PMID 28276512, 2017). "Non-users of statins were significantly younger, more likely to be female and had a significantly shorter duration of diabetes and insulin use." (PMID 28830436, 2017). "These experimental studies were combined with mathematical modelling ina systems approach to compare the insulin-signalling network in the normal statewith the same network in the insulin-resistant state of diabetes." (PMID 27986865, 2017). "Type 1 Diabetes Mellitus (T1DM), the most severe form of diabetes mellitus, is a disorder triggered by environmental factors that results in the autoimmune attack against the insulin-producing ß cells localized in the pancreatic islets of Langerhans." (PMID 28729721, 2017). "Diabetes mellitus is a group of diseases characterized by hyperglycemia due to defects in insulin secretion, insulin action, or both." (PMID 31384248, 2017). "Our results confirm the essential role of low insulin sensitivity in the development of incident diabetes." (PMID 28409212, 2017). "It is thus likely that a lower albumin level promotes diabetes-induced muscle weakness, followed by cytokine-induced impairment of insulin secretion in pancreas, and elevation of circulating glucose levels." (PMID 28360943, 2017). "Pre-diabetes is increasingly recognised as a disease state, and proinsulin or the proinsulin:insulin and proinsulin:C-peptide ratios as markers for it." (PMID 28426711, 2017). "Fasting glucose and fasting insulin are glycemic traits closely related to diabetes, and understanding the role of genetic factors in these traits can help reveal the etiology of type 2 diabetes." (PMID 28789618, 2017).